SETD2 (SET domain containing 2, histone lysine methyltransferase)
Description:
Histone methyltransferase that specifically trimethylates 'Lys-36' of histone H3 (H3K36me3) using dimethylated 'Lys-36' (H3K36me2) as substrate. It is capable of trimethylating unmethylated H3K36 (H3K36me0) in vitro. Represents the main enzyme generating H3K36me3, a specific tag for epigenetic transcriptional activation (By similarity). Plays a role in chromatin structure modulation during elongation by coordinating recruitment of the FACT complex and by interacting with hyperphosphorylated POLR2A. Acts as a key regulator of DNA mismatch repair in G1 and early S phase by generating H3K36me3, a mark required to recruit MSH6 subunit of the MutS alpha complex: early recruitment of the MutS alpha complex to chromatin to be replicated allows a quick identification of mismatch DNA to initiate the mismatch repair reaction. Required for DNA double-strand break repair in response to DNA damage: acts by mediating formation of H3K36me3, promoting recruitment of RAD51 and DNA repair via homologous recombination (HR). Acts as a tumor suppressor. H3K36me3 also plays an essential role in the maintenance of a heterochromatic state, by recruiting DNA methyltransferase DNMT3A. H3K36me3 is also enhanced in intron-containing genes, suggesting that SETD2 recruitment is enhanced by splicing and that splicing is coupled to recruitment of elongating RNA polymerase. Required during angiogenesis (By similarity). Required for endoderm development by promoting embryonic stem cell differentiation toward endoderm: acts by mediating formation of H3K36me3 in distal promoter regions of FGFR3, leading to regulate transcription initiation of FGFR3 (By similarity). In addition to histones, also mediates methylation of other proteins, such as tubulins and STAT1. Trimethylates 'Lys-40' of alpha-tubulins such as TUBA1B (alpha-TubK40me3); alpha-TubK40me3 is required for normal mitosis and cytokinesis and may be a specific tag in cytoskeletal remodeling. Involved in interferon-alpha-induced antiviral defense by mediating both monomethylation of STAT1 at 'Lys-525' and catalyzing H3K36me3 on promoters of some interferon-stimulated genes (ISGs) to activate gene transcription. (Microbial infection) Recruited to the promoters of adenovirus 12 E1A gene in case of infection, possibly leading to regulate its expression.
Synonyms: HIP-1; HYPB; KIAA1732; KMT3A; SET2; HSPC069; HIF-1; FLJ23184; HBP231; LLS; MRD70; RAPAS; p231HBP
Tractability: Small molecule: a structure with a bound ligand is known; a high-quality ligand is known. PROTAC: UniProt records ubiquitination sites on it; ubiquitination databases record sites on it; its protein half-life has been measured; a small molecule that binds it is known.
Target class: Writer; Protein methyltransferase; SET domain; Epigenetic regulator
Chemical probes: EPZ-719 (high quality)
Gene: Protein-coding gene on chromosome 3 (47,016,428 to 47,164,113, reverse strand). Ensembl gene ENSG00000181555.
Subcellular location: Nucleus; Chromosome
Subcellular location (Human Protein Atlas): Nuclear speckles; Cytosol
Pathways (Reactome):
Chromatin organization: PKMTs methylate histone lysines
Gene Ontology:
Molecular function: alpha-tubulin binding; histone H3K36 methyltransferase activity; histone H3K36 trimethyltransferase activity; protein binding; protein-lysine N-methyltransferase activity; histone H3 methyltransferase activity; histone methyltransferase activity
Biological process: defense response to virus; microtubule cytoskeleton organization involved in mitosis; mismatch repair; nucleosome organization; peptidyl-lysine trimethylation; positive regulation of autophagy; positive regulation of interferon-alpha production; regulation of cytokinesis; regulation of double-strand break repair via homologous recombination; regulation of mRNA export from nucleus; regulation of protein localization to chromatin; response to type I interferon; transcription elongation by RNA polymerase II; endodermal cell differentiation; regulation of gene expression; stem cell differentiation; positive regulation of ossification; regulation of DNA-templated transcription; response to alkaloid; response to metal ion
Cellular component: chromosome; cytoplasm; nucleoplasm; nucleus; nuclear lumen
Genetic constraint (gnomAD): Loss-of-function variants: 28 observed, 218.6 expected, observed/expected ratio (o/e) 0.13, 90% interval 0.094 to 0.18. The upper end of that interval is the gene's LOEUF score, 0.18, which puts it in group 1 of 6, group 1 being the genes least tolerant of losing a copy. Missense variants: 2,420 observed, 3,048.5 expected, observed/expected ratio (o/e) 0.79, 90% interval 0.77 to 0.82. Synonymous variants: 981 observed, 1,085.2 expected, observed/expected ratio (o/e) 0.9, 90% interval 0.86 to 0.95.
Gene-disease validity (ClinGen):
ClinGen rates the evidence that SETD2 causes each of these diseases.
SETD2-related neurodevelopmental disorder without or with macrocephaly/overgrowth (autosomal dominant): Definitive.
Cancer hallmarks: invasion and metastasis (suppresses); genome instability and mutations (suppresses); change of cellular energetics; angiogenesis (promotes); suppression of growth (promotes); tumour promoting inflammation; proliferative signalling (promotes); escaping programmed cell death (suppresses); escaping immune response to cancer; tumour promoting inflammation (suppresses); escaping programmed cell death (promotes)
Homologues: Orthologues: chimpanzee SETD2 (99% identical), macaque SETD2 (98% identical), dog SETD2 (92% identical), pig SETD2 (90% identical), guinea pig SETD2 (89% identical), rat Setd2 (85% identical), mouse Setd2 (81% identical), tropical clawed frog setd2 (53% identical), Drosophila melanogaster Set2 (22% identical), Caenorhabditis elegans met-1 (9% identical), Caenorhabditis elegans set-19 (5% identical), Drosophila melanogaster G9a (5% identical), and 9 more. Paralogues in human: NSD1 (14% identical), NSD3 (11% identical), NSD2 (11% identical), ASH1L (10% identical), KMT2A (7% identical), KMT2D (6% identical), KMT2C (5% identical), KMT2B (5% identical), EZH2 (5% identical), EHMT1 (5% identical), EHMT2 (5% identical), EZH1 (5% identical), and 7 more.
Diseases named in the same sentence as SETD2 in open-access papers:
SETD2 is named in the same sentence as 237 diseases in open-access papers, as found by Europe PMC text mining. Sharing a sentence is not in itself a finding about the gene and the disease. The quoted sentences say what the papers report.
clear cell renal cell carcinoma (64 papers, 2011 to 2026). "We focused on clear cell renal cell carcinoma (ccRCC), as a cancer where SETD2 mutations contribute to tumorigenesis, and lung adenocarcinoma, where SETD2 mutations are also known to occur." (PMID 40961184, 2025). "Loss of SETD2 has also recently been shown to increase lipid peroxidation and ROS levels in clear cell renal carcinoma." (PMID 39921567, 2025). "Histone‐lysine N‐methyltransferase SETD2 (SETD2), the sole histone methyltransferase that catalyzes trimethylation of lysine 36 on histone H3 (H3K36me3), is often mutated in clear cell renal cell carcinoma (ccRCC)." (PMID 37418588, 2024). "Mutations of SETD2 were observed and extensively studied in certain malignancies, such as clear-cell renal-cell carcinoma (ccRCC), colorectal cancer, lungs, gastric, glioma, and colorectal cancer." (PMID 38611113, 2024). "Histone methyltransferase SETD2 catalyzes H3K36me3 at gene bodies and when mutated is associated with poor outcome in clear cell renal cell cancer." (PMID 37418588, 2024). "Somatic SETD2 mutations occur in a range of human cancers, in particular clear cell renal cell carcinomas (ccRCCs)." (PMID 37166351, 2023). "In clear cell renal cell carcinoma (ccRCC), SETD2 mediates the trimethylation of α-tubulin at K40, which is required to maintain genomic stability, and loss of SETD2 function results in genomic instability and contributes to ccRCC tumorigenesis." (PMID 38036730, 2023). "SETD2 mutations have been documented in several cancers, including clear cell renal cell carcinoma (ccRCC)." (PMID 37025591, 2023). "MPM has similarities to clear cell renal cell carcinoma (ccRCC), as both harbour frequent loss of function mutations in SETD2, SETD5 and BAP1, and we confirm in this study PBRM1." (PMID 35637530, 2022). "Inactivating mutations in the SETD2 gene and impaired autophagic flux are frequent molecular and cellular features in clear cell renal cell carcinoma (ccRCC)." (PMID 36371383, 2022). "Mutations in SETD2 (both mono- and bi-allelic) have been found in many cancer types, including clear cell renal cell carcinoma (ccRCC), gliomas, and in several types of leukemia." (PMID 35661267, 2022). "VHL and PBRM1 are major genes that cause mutations in more than 40% of clear cell renal cell carcinoma, and SETD2 and PTEN, which are quite frequent, are genes that cause both copy number loss and mutation." (PMID 33905431, 2021). "Consistent with its functionally important role, SETD2 deletion is embryonically lethal and mutations in SETD2 have been reported in many cancers, including clear cell renal cell carcinoma." (PMID 34391778, 2021). "Recent studies identified SETD2 functions as a tumor suppressor in kidney cancer, which was frequently inactivated and associated with the recurrence of clear cell renal cell carcinoma." (PMID 33790054, 2021). "For example, the SETD2 tumor suppressor is frequently mutated subclonally in clear cell renal cell carcinomas, as observed previously in multi-region sequencing experiments, and in pancreatic neuroendocrine cancers." (PMID 33831375, 2021). "Clinically, SETD2 mutations are most prevalent in clear cell renal carcinomas but are also less commonly seen in hematopoietic cancers, high-grade glioma, melanoma, and adenocarcinomas of the lung and gastrointestinal system." (PMID 34925233, 2021). "Another cancer type in which SETD2 plays an important role is Sporadic clear cell renal cell carcinoma (cRCC), where frameshift, non-sense and missense mutations in SETD2 were observed, suggesting a loss-of-function mechanism." (PMID 32939018, 2020). "Inactivating SETD2 mutations are common in clear cell renal cell carcinomas, but have been described at low frequencies across additional tumor types." (PMID 31899853, 2020). "Most frequently, SETD2 mutations are seen in clear cell renal cell carcinoma (CCRCC) and are thought to confer a poor prognosis." (PMID 30419952, 2018).
clear cell renal cell carcinoma (continued). "NSD1 inactivation along with SETD2 mutation that causes a distorted H3K36 is a key feature of clear cell renal cell carcinoma." (PMID 30466474, 2018). "Clear cell renal cell carcinomas (ccRCCs) harbor frequent mutations in epigenetic modifiers including SETD2, the H3K36me3 writer." (PMID 26646321, 2016). "The presence of inactivating mutations in a range of tumor types, most notably in clear cell renal cell cancer (ccRCC), sparked an additional focus of research: exploring the role of SETD2 in cancer development." (PMID 27191891, 2016). "A high frequency of SETD2 mutations was recently disclosed in several cancers, of which clear cell renal cell carcinoma (ccRCC) shows the highest SETD2 mutation rate." (PMID 24843002, 2014). "SETD2 mutations were recently found in several cancers, such as clear cell renal cell carcinoma (ccRCC)." (PMID 24843002, 2014). "Numerous tumors are associated with SETD2 genetic alterations, including clear-cell renal carcinomas which show the highest mutation frequency among SETD2-related cancers, but also leukemias and lymphomas, non-small-cell lung tumors, gastric tumors and gliomas." (PMID 39591760, 2025). "A recent study further revealed that SETD2 deficiency in renal tissues alters the metabolic microenvironment by affecting glycolysis, lipid metabolism, and sphingomyelin biosynthesis, thereby contributing to the development of clear cell renal cell carcinoma." (PMID 41013841, 2025). "Besides, SETD2 is associated with development and progression of several cancers, such as clear cell renal cell carcinoma, breast carcinoma and colorectal cancer, and is involved in chemotherapy resistance in some patients with tumor 7,10-12." (PMID 39668826, 2024). "In addition, SETD2 mutation is associated with the development and progression of several cancers, such as clear cell renal cell carcinoma, breast carcinoma and colorectal cancer, and is involved in chemotherapy resistance in leukemia patients 7,10-12." (PMID 39668826, 2024). "Understanding the impact of loss or depletion of SETD2 and H3K36me3 on DNA methylation is of particular clinical relevance as SETD2 is frequently mutated in multiple cancer types, for example, in up to 16% of clear cell renal cell carcinomas (ccRCC) and can be as high as 30% in metastatic ccRCC." (PMID 37528416, 2023). "A genome-wide transcriptome analysis in SETD2 deficient and proficient primary clear cell renal cell carcinoma (ccRCC) tumors revealed that splicing defects or alternative splicing events such as intron inclusion and differential exon usage are widespread in SETD2 deficient tumors." (PMID 35661267, 2022). "Enteropathy-associated T cell lymphoma (EATL) is an aggressive, often lethal cancer, which can arise from celiac disease, and mutations in SETD2 are found in 32% of cases, while in clear cell renal carcinomas (ccRCC), deletions or mutations of SETD2 are also found." (PMID 35406676, 2022). "Consistently, herpes simplex virus (HSV) infection and SETD2 mutation in clear cell renal cell carcinoma, which disrupt transcriptional termination, both generate extended host gene transcripts between adjacent genes that are often spliced between normally separate TUs." (PMID 33735606, 2021). "Furthermore, studies have implicated H3K36me3 in alternative splicing in human cell culture and inefficient intron splicing in clear cell renal cell carcinomas, again via SETD2 mutation." (PMID 28346137, 2017). "In addition to pediatric cerebral GBM, inactivating mutation of SETD2 has been reported as a driver gene mutation in clear cell renal cell carcinoma (ccRCC), leukemia, and breast cancer." (PMID 28852847, 2017). "Finally, we describe the prevalence of SETD2-inactivating mutations in cancer, with the highest frequency in clear cell Renal Cell Cancer, and explore how SETD2-inactivation might contribute to tumor development." (PMID 27191891, 2016).
clear cell renal cell carcinoma (continued). "Clear cell renal cell carcinoma (ccRCC) is characterized by near ubiquitous loss of VHL followed by mutations in epigenetic regulators PBRM1, SETD2, and BAP1." (PMID 39874221, 2025). "For instance, SETD2 has been shown to maintain genomic stability and enhance DNA damage repair in clear cell renal cell carcinoma." (PMID 38036730, 2023). "In past decades, the study of H3K36me3 and SETD2 mainly focus on their function as tumor suppressors, including clear cell renal cell carcinoma, chondroblastomas, lymphoma, acute leukemia, intestinal tumorigenesis, and so on." (PMID 30422989, 2018). "Inactivation of human SET domain containing protein 2 (SETD2) is a common event in clear cell renal cell carcinoma (ccRCC)." (PMID 25714014, 2015). "In agreement, SETD2-mutant clear cell renal cell carcinoma (ccRCC) cells displayed impaired DNA damage signaling." (PMID 24843002, 2014). "However, in more than 90% of sporadic clear cell renal cell carcinomas, loss of chromosome 3p, which harbors tumor suppressors VHL on 3p25 and PBRM1, BAP1, and SETD2 on 3p21, is an established occurrence." (PMID 39281855, 2024). "Conversely, loss-of-function mutations in epigenetic modulators such as HMT, SETD2 results in metabolic dysregulations such as aerobic glycolysis and increased TCA cycle metabolite flux as observed in clear cell renal carcinoma, which are key features of metabolic rewiring in cancer cells." (PMID 35382567, 2022). "In clear cell renal cell carcinoma, it is demonstrated that total H3K36me3 levels are not significantly impacted by monoallelic loss of SETD2." (PMID 33260897, 2020). "Inactivating mutations in the SETD2 gene, encoding for a nonredundant histone H3 methyltransferase and regulator of transcription, is a frequent molecular feature in clear cell renal cell carcinomas (ccRCC)." (PMID 31988284, 2020). "Whereas VHL inactivation is a primary event in clear cell renal cell carcinoma (ccRCC), the precise mechanism(s) of how this interacts with the secondary mutations in tumor suppressor genes, including PBRM1, KDM5C/JARID1C, SETD2, and/or BAP1, remains unclear." (PMID 30355451, 2018). "Renal clear cell carcinoma tumors with SETD2 mutations had DNA hypomethylation at non-promoter regions that are marked by H3K36me3." (PMID 30466474, 2018). "Clear cell Renal Cell Carcinoma (ccRCC) is due to loss of von Hippel–Lindau (VHL) gene and at least one out of three chromatin regulating genes BRCA1-associated protein-1 (BAP1), Polybromo-1 (PBRM1) and Set domain-containing 2 (SETD2)." (PMID 26452128, 2015). "Similar to benign renal cysts, hemangioblastomas rarely demonstrate aggressive malignant features, and we did not detect additional clonal genetic drivers in hemangioblastomas, including other candidate genomic loci on chromosome 3p of BAP1, SETD2, and PBRM1 implicated in clear cell renal carcinoma." (PMID 25589003, 2014). "Specifically, studies of clear cell renal cell carcinoma indicate that mutations occurring at higher AFs may not result in significant decreases in H3K36me3 unless both SETD2 alleles are affected." (PMID 30419952, 2018). "PBRM1, SETD2, and BAP1 were previously known HNSC genes and recently found to be altered in clear cell renal cell carcinoma." (PMID 28938536, 2017). "However, the original LEDGF recognition H3K36me3 epigenetic regulatory axis no longer exists in SETD2 mutant clear cell renal cell carcinoma (ccRCC) patients, and a new transcription system needs to be discovered." (PMID 40548925, 2025).